RN7SL191P (RNA, 7SL, cytoplasmic 191, pseudogene)
Gene: Miscellaneous RNA gene on chromosome X (131,134,086 to 131,134,390, reverse strand). Ensembl gene ENSG00000241198.
Homologues: Orthologues: chimpanzee Metazoa_SRP (99% identical), macaque Metazoa_SRP (91% identical). Paralogues in human: RN7SL1 (80% identical), RN7SL2 (80% identical), RN7SL709P (79% identical), RN7SL586P (79% identical), RN7SL665P (78% identical), RN7SL3 (78% identical), RN7SL45P (78% identical), RN7SL122P (77% identical), RN7SL508P (77% identical), RN7SL566P (77% identical), RN7SL597P (77% identical), RN7SL7P (77% identical), and 703 more.